INSM1 (INSM transcriptional repressor 1)
Diseases named in the same sentence as INSM1 in open-access papers (continued):
Sharing a sentence is not in itself a finding about the gene and the disease.
pancreatic neuroendocrine tumor (6 papers, 2007 to 2025). Pancreatic endocrine tumor, also known as pancreatic neuroendocrine tumor (PNET), describes a group of endocrine tumors originating in the pancreas that are usually indolent and benign, but may have the potential to be malignant. "At this point, insulinoma-associated protein 1 (INSM1) expression is often found in pancreatic neuroendocrine tumors." (PMID 40565772, 2025). "Consistent with previously published findings, genes with significantly elevated expression in islet cell tumors included insulinoma-associated 1 (INSM1), glutaminyl-peptide cyclotransferase (QPCT), fibrinogen B beta polypeptide (FGB), peroxisomal biogenesis factor 7 (PEX7)." (PMID 17389914, 2007). "The markers (SYP, CGA, and INSM1) were evaluated with both pure primary pancreatic NET and mixed adenoneuroendocrine carcinoma (MiNEN, which contains both NET and carcinoma components)." (PMID 34943408, 2021). "In pancreatic NETs, INSM1 is more sensitive and specific than conventional markers in differentiating NETs from non-NET tumors." (PMID 34943408, 2021). "Islet cell hyperplasia in a background of chronic pancreatitis can be misinterpreted as pancreatic NET and INSM-1 can facilitate a misdiagnosis." (PMID 34943408, 2021). "The results for INSM1 expression was identical for both pancreatic NETs on cell block and surgical resection." (PMID 34943408, 2021). "The pancreatic NET grades have shown to be inversely correlated with INSM1 nuclear expression." (PMID 34943408, 2021). "All control cases with the exception of the lymph nodes involved with NE tumors (one carcinoid of small bowel, two small cell carcinoma, and pancreatic NET primary) were negative for INSM1." (PMID 34943408, 2021). "INSM1 displayed 100% sensitivity, specificity, PPV, and NPV for differentiating pancreatic NETs from non-NE pancreatic tumors." (PMID 34943408, 2021).
carcinoids (5 papers, 2019 to 2025). "ASCL1 is preferentially observed in pulmonary HG-NECs, less frequently in carcinoid tumors, while INSM1 is constantly expressed in all pulmonary NE tumors with even higher sensitivity in carcinoid." (PMID 34996493, 2022). "In one study, in the cohort of carcinoid tumors, the sensitivity of INSM1 was lower than all other markers (90% vs. 100% each), while another study found that all markers stained 100% of carcinoid tumors." (PMID 34943408, 2021). "INSM1 has been found to have high sensitivities in carcinoid tumors, ranging from 98-100% across many studies." (PMID 34943408, 2021). "In a large cohort of 402 lung tumors, including typical and atypical carcinoids, LCNECs, SCLCs, and thoracic paragangliomas, INSM1 performed at a 76% sensitivity and 99% specificity." (PMID 34943408, 2021). "INSM1 tends to show high sensitivities overall but appears to underperform in comparison to CD56 and SYP in certain lung NETs such as carcinoid tumors and LCNECs." (PMID 34943408, 2021). "In a study that tested both markers in typical carcinoids, atypical carcinoids, SCLCs, and LCNECs, researchers found that though the overall sensitivity of STX1 in these samples was very high (96.6%), INSM1 outperformed the marker (97.7%)." (PMID 34943408, 2021). "Notably, INSM1 has been demonstrated to be highly expressed in SCLC, carcinoid tumors, and in the SCLC-like molecular subtype of LCNEC, while generally absent in non-neuroendocrine NSCLCs." (PMID 40805240, 2025). "However, even carcinoid tumors expressing SYP and CgA may occasionally lack INSM1 expression." (PMID 39937015, 2025). "Subsequent studies demonstrated INSM1 expression in SCLC, LCNEC, and carcinoid tumors, but not in NSCLC lacking NE differentiation." (PMID 40805240, 2025). "For carcinoids, in contrast to diffuse expression of INSM1, SYN, CGA and CD56 in most of the cases, positivity staining of SOX11 was observed in none of typical carcinoids (0/25) and only 1/12 of atypical carcinoids." (PMID 34996493, 2022).
small cell carcinoma (5 papers, 2021 to 2025). A neuroendocrine carcinoma composed of small malignant cells which are often said to resemble "oat cells" under the microscope. "Disease progression occurred after 12.5 months, and repeat lung biopsy revealed small cell carcinoma (TTF-1+/synaptophysin+/INSM1+; Ki-67 85%)." (PMID 41256964, 2025). "Overall, INSM1 was more sensitive for the detection of small cell carcinomas than for large cell NE carcinoma (93.9% vs. 62.5% (6/8), p = 0.015) of genitourinary tract." (PMID 34943408, 2021). "Biopsy was done and the pathology confirmed small cell carcinoma, strongly positive for cytokeratin (AE1/AE3) and insulinoma-associated protein 1 (INSM-1), scatteredly positive for chromogranin A, synaptophysin and CD56." (PMID 34477164, 2021). "INSM1 showed similar sensitivity (93.9%) to SYN (93.9%), CgA (87.8%), and CD56 (87.8%) in all 33 small cell carcinomas or carcinomas with small cell carcinoma components." (PMID 34943408, 2021). "POU2F3-driven small cell carcinomas are biologically distinct, characterized by the absence of classic neuroendocrine lineage markers, including synaptophysin, chromogranin and INSM1 and the expression of tuft cell lineage markers." (PMID 40931642, 2025). "In a study on 49 gynecologic NECs (4 vagina, 39 cervix, 5 cases of endometrium, and 1 ovary), INSM1 expression was more diffuse and intense compared to SYN, CgA, and CD56 for cervical small cell NECs but not for large cell NECs." (PMID 34943408, 2021).
squamous cell carcinoma (5 papers, 2021 to 2025). A carcinoma arising from squamous epithelial cells. "Despite its utility, INSM1 is ectopically expressed in a limited number of squamous cell carcinomas, acinic cell carcinomas, mucoepidermoid carcinomas, and sinonasal adenocarcinomas of the head and neck." (PMID 39937015, 2025). "Squamous cell carcinoma is sometimes focally and weakly positive for INSM-1." (PMID 34943408, 2021). "The specificity of Musashi-1 for lung NEC tested with adenocarcinoma and squamous cell carcinoma (81%) was comparable to those of synaptophysin (82%) and CD56 (81%) and lower than those of chromogranin (96%) and INSM1 (87%)." (PMID 38067335, 2023). "Expression of neuroendocrine markers such as synaptophysin, INSM1, and CD56 confirmed neuroendocrine differentiation, while negative p40 ruled out poorly differentiated squamous cell carcinoma." (PMID 40909459, 2025).
large cell neuroendocrine carcinoma (4 papers, 2021 to 2025). A usually aggressive carcinoma composed of large malignant cells which display neuroendocrine characteristics. "In large-cell neuroendocrine carcinoma, CD56 and SYP demonstrated greater sensitivity than INSM1, whereas CgA showed lower sensitivity." (PMID 39937015, 2025).
lung NETs (4 papers, 2020 to 2025). "Recent studies have suggested that INSM1 has high diagnostic accuracy in identifying pulmonary neuroendocrine neoplasms, particularly SCLC and LCNEC, with reported sensitivity ranging from 68% to 95% and specificity from 95% to 99%." (PMID 40805240, 2025). "INSM1 has been proposed not only as a useful adjunct but also as a potential first-line marker for confirming neuroendocrine differentiation in pulmonary neuroendocrine neoplasms, particularly SCLC and LCNEC." (PMID 40805240, 2025). "In a large study of 345 primary lung neoplasms, INSM1 was found to have a specificity for lung NETs (97%) which is similar to CGA (98%), but greater than CD56 (87%) and SYP (90%)." (PMID 34943408, 2021). "In another cohort of 54 lung NETs, INSM1 performed lower than CD56 (87%), higher than CGA (56%), and lower than SYP (85%)." (PMID 34943408, 2021). "Overall, INSM1 presents itself as a reliable immunostain for the diagnosis of SCLCs and other lung NETs, but more studies are necessary before it can replace traditional NE markers." (PMID 34943408, 2021). "Regarding other lung NETs, multiple studies have compared INSM1 sensitivity and specificity to existing markers, but a universal consensus on the immunostain’s performance has yet to be reached." (PMID 34943408, 2021). "Overall, INSM1 shows high sensitivity and specificity for the diagnosis of lung NETs." (PMID 34943408, 2021). "The diagnosis of neuroendocrine lung tumors relies upon histological examination and immunohistochemical detection of general markers of neuroendocrine differentiation such as chromogranin A, synaptophysin, neuroendocrine cell adhesion molecule (NCAM) and insulinoma associated protein 1 (INSM1)." (PMID 33375066, 2020). "INSM1 has been reported to have excellent sensitivity and specificity for the diagnosis of lung NETs, and no cases of NSCLC have reported to be positive for ASCL1 immunostaining so far." (PMID 33968782, 2021). "Multiple studies have reported comparisons of INSM1 sensitivity and specificity with those of CD56, SYP, and CGA in lung NETs, but there does not yet appear to be a universal consensus on INSM1′s performance." (PMID 34943408, 2021).
medullary thyroid carcinoma (4 papers, 2021 to 2025). "In addition to medullary carcinoma and its mimickers, INSM1 was successfully applied as a NE marker in C-cell hyperplasia." (PMID 34943408, 2021). "The negative GATA3 and INSM1 staining in this case excluded parathyroid lesions and medullary thyroid carcinoma." (PMID 41476594, 2025).
Merkel cell carcinoma (4 papers, 2019 to 2025). "Regarding Merkel cell carcinoma, INSM1 has been shown to stain more diffusely and intensely than markers such as SYP, CGA, and CD56." (PMID 34943408, 2021). "Here, we show that MCPyV+ Merkel cell carcinoma is defined by neuroendocrine-lineage core regulatory (CR) transcription factors (TFs) (ATOH1, INSM1, ISL1, LHX3, POU4F3, and SOX2) that were essential for tumor survival and that co-bound chromatin with the viral small T antigen at super enhancers." (PMID 41392987, 2025). "The nuclei of the carcinoma had a smudged, salt-and-pepper appearance; however, CK20, INSM-1, and synaptophysin were negative, excluding Merkel cell carcinoma." (PMID 41019495, 2025). "However, CK20, synaptophysin, and INSM-1 are all negative, excluding Merkel cell carcinoma." (PMID 41019495, 2025).
prostate carcinoma (4 papers, 2024 to 2025). A carcinoma that arises from epithelial cells of the prostate gland. "The relationship between INSM1, EGFR, and cell cycle has been confirmed to be a key factor in NE transformation of prostate cancer." (PMID 40437627, 2025).
adenoma (3 papers, 2021 to 2025). A neoplasm arising from the epithelium. "We compared the invasion-related molecular markers in various subtypes of NF-PitNEts and found that HSPA2 and INSM1 expression was higher in SCAs than SGAs or null cell adenomas (P < 0.0001)." (PMID 33391466, 2021). "The present tumor was initially suspected to be a corticotrophin tumor/adenoma based on Cushing's manifestations and histological findings, which showed well‐differentiated nests of pituitary cells with positive Syn, INSM‐1, and T‐PIT lineage markers (including T‐PIT and ACTH)." (PMID 40040389, 2025). "Insulinoma-associated protein 1 (INSM1) is absent both from normal and pathological parathyroid tissues including multiglandular parathyroid disease in primary hyperparathyroidism, secondary hyperplasia, tertiary hyperparathyroidism, adenomas, atypical adenomas and carcinomas." (PMID 35805976, 2022).
diabetes (3 papers, 2018 to 2021). "Understanding of the regulatory mechanisms of critical transcriptional factors, such as Ngn3, NeuroD1, and Insm1, in islet development is important for making insulin-producing cells for prospective stem cell therapy to treat diabetes." (PMID 30359270, 2018). "Furthermore, several genes involved in the endocrine specification and diabetes development were significantly downregulated, such as HES1, INSM1, HNF1A, NEUROD1, NGN3, NKX2.2, GIPR, MNX1, PROX1, TCF7L2, and HHEX." (PMID 33473118, 2021).
lung carcinoid tumor (3 papers, 2019 to 2024). A neuroendocrine neoplasm that arises from the lung. "To further examine its role in transcriptional regulation, we measured the mRNA levels of a common set of YAP target genes in a lung carcinoid tumor cell line (H727) with high endogenous INSM1 expression." (PMID 30901309, 2019). "To further ensure consistency of key expression patterns, we compare expression values of four markers of lung carcinoid tumors: NCAM1 (CD35), INSM1, SYP (synaptophysin), and OTP (orthopedia homeobox protein)." (PMID 38706317, 2024). "From an immunohistochemical viewpoint, lung carcinoids are positive for pan-cytokeratins and neuroendocrine markers of first- (CD56, chromogranin A, and synaptophysin) and second-generation lineages (INSM1)." (PMID 38001701, 2023).
pancreatic cancer (3 papers, 2021 to 2024). "Overexpression of INSM1 inhibits the binding of cyclin D1 and CDK4, induces cell cycle arrest, and inhibits the growth of panc-1 pancreatic cancer cell line." (PMID 36531655, 2022). "Overexpression of the islet-specific transcription factors (ITFs) INSM1, Pdx-1, and NeuroD1 in the AR42J pancreatic tumor cell line results in higher levels of differentiation into insulin-positive cells and the activation of Ngn3 and MafA." (PMID 34943408, 2021).
pheochromocytoma (3 papers, 2022 to 2025). "Immunoreactivity to classic neuroendocrine markers such as CgA and synaptophysin is almost always present, and second-generation neuroendocrine markers ISL LIM Homeobox 1 (ISL1) and INSM1 have also been found as reliable markers of an adrenal medullary origin in pheochromocytoma." (PMID 35205664, 2022). "Pheochromocytomas and abdominal paragangliomas stain positive for neuroendocrine markers CgA, SYP, ISL1, INSM1 and, often, GATA3; subsets of cases may display an intricate network of supporting sustentacular cells which are highlighted by an S100 or SOX10 stain." (PMID 37685605, 2023).
sarcoma (3 papers, 2021 to 2023). A usually aggressive malignant neoplasm of the soft tissue or bone. "A study on 28 SFT cases found that INSM1 was reactive in 21% (6/28) of the cases, which was slightly superior to desmin (14.3%, 4/28) and p16 (17.9%, 5/28), suggesting differential diagnosis of sarcomas can be supplemented by the use of the INSM1 marker." (PMID 36531655, 2022). "Differential diagnosis of sarcomas can also be supplemented by the use of the INSM1 marker." (PMID 34943408, 2021). "Multiple genes were downregulated (p < 0.05) in sarcoma tumors, including HSP90AB1, IGHA1, INSM1, IRF5, MAP2K2, and SEH1L." (PMID 37445737, 2023).
thoracic tumors (3 papers, 2021 to 2023). "The lower end of INSM1′s sensitivity and specificity has been found to be 81.5% and 82.7%, respectively; however, INSM1 positivity higher than the minimum diagnostic threshold was observed in rare thoracic tumors that have a morphologic overlap with SCLCs." (PMID 34943408, 2021). "Another marker of neuroendocrine differentiation, Insulinoma-associated Protein 1 (INSM1), has been reported to support the diagnosis of neuroendocrine differentiation in thoracic tumors and has the potential to complement the currently recommended neuroendocrine markers." (PMID 33933015, 2021).
breast neoplasm (2 papers, 2021). A benign or malignant neoplasm of the breast parenchyma. "Discussion: Syntaxin-1 and INSM1 are sensitive and specific markers of breast tumors with neuroendocrine features, outperforming chromogranin A and CD56." (PMID 34764822, 2021). "More recently, INSM1 has emerged as sensitive biomarker for the detection of neuroendocrine differentiation in breast neoplasms." (PMID 34943408, 2021). "Altogether, we believed that the few dozens of cases investigated were sufficient to validate the concept of STX1 and to a lesser extent of INSM1 as suitable NE markers of breast tumors, even if we were unable to formulate statements concerning the exceptionally rare primary mammary NETs or NECs." (PMID 34764822, 2021).
glioblastoma (2 papers, 2023 to 2025). The most malignant astrocytic tumor (WHO grade IV). "INSM1 is highly expressed in human glioblastoma tumors and, during cortical development, in intermediate progenitor cells, which give rise to neurons." (PMID 41354838, 2025). "Our results indicate that immunohistochemical detection of EGFR, MEOX2, SOX11, and INSM1 can be useful for detection of glioblastoma cells in limited histological samples, especially when used in combination." (PMID 37568909, 2023). "To test the generalizability of INSM1’s metabolic and malignant roles in GBM, we used primary glioblastoma stem-like cells (GSCs) as a complementary model system." (PMID 41354838, 2025).
liposarcoma (2 papers, 2022 to 2024). A usually painless malignant tumor that arises from adipose tissue. "INSM1 may be involved in the regulation of liposarcoma development." (PMID 36531655, 2022). "The mechanism of interaction between INSM1 and CDK4 may be involved in the development of liposarcoma, which needs to be further explored." (PMID 36531655, 2022). "Moreover, INSM1 expression in well-differentiated liposarcoma (WDLPS) was significantly higher than normal fat (P = 0.014) and dedifferentiated liposarcoma (DDLPS) (P = 0.0248)." (PMID 36531655, 2022).
lung neoplasm (2 papers, 2021 to 2025). A benign or malignant, primary or metastatic neoplasm involving the lungs. "Several studies have assessed the diagnostic performance of INSM1 in pulmonary NECs, reporting high sensitivity and specificity for distinguishing SCLC and LCNEC from other lung tumors." (PMID 40805240, 2025). "INSM1 has recently emerged as a reliable immunostain of NE differentiation in lung neoplasms as well." (PMID 34943408, 2021). "INSM1 has recently emerged as a reliable prognostic immunostain of neuroendocrine differentiation in human lung neoplasms." (PMID 34943408, 2021).
mesenchymal tumor (2 papers, 2021 to 2022). "Therefore, whether INSM1 can continue to maintain excellent diagnostic performance in mesenchymal tumors is indeed a question worth exploring." (PMID 36531655, 2022). "We analyzed INSM1 mRNA level in GEO database and conducted immunohistological staining to detect the expression of INSM1 on 576 mesenchymal tumors from pathology department of Tongji Hospital." (PMID 36531655, 2022). "Here, we use immunohistochemical method to detect the expression of INSM1 in 576 mesenchymal tumors." (PMID 36531655, 2022). "Here, our study systematically explored the expression of INSM1 in different mesenchymal tumors, laying a foundation for the diagnosis and targeted therapy of INSM1 in mesenchymal tumors." (PMID 36531655, 2022). "The study on the expression of INSM1 in mesenchymal tumors is still limited." (PMID 36531655, 2022). "However, whether INSM1 can become a therapeutic target in mesenchymal tumors lacks theoretical and experimental bases." (PMID 36531655, 2022). "Specifically, when differentiating extraskeletal myxoid chondrosarcoma (EMC) from other mesenchymal tumors, INSM1 shows 90% positive staining with EMC but was negative with 94% of the other mesenchymal tumor samples of various cell types." (PMID 34943408, 2021). "Finally, the function of INSM1 in non-NETs was not clear, and this study lacks deeper insights on how INSM1 expression influences the mesenchymal tumors." (PMID 36531655, 2022).
metastatic tumors (2 papers, 2019 to 2023). "Altogether, the presence of metastatic tumors was 3.3-fold more common in the animals injected with the cell line knocked out for Insm1." (PMID 30796198, 2019).
myxoid chondrosarcoma (2 papers, 2020 to 2022). A chondrosarcoma characterized by the presence of myxoid changes. "INSM1 is highly expressed in the extraskeletal myxoid chondrosarcoma and is a potential molecular marker for its diagnosis." (PMID 32670859, 2020).